KLK4 (kallikrein related peptidase 4)
Diseases named in the same sentence as KLK4 in open-access papers (continued):
Sharing a sentence is not in itself a finding about the gene and the disease.
prostate carcinoma (continued). "To shed light on a potential role for KLK4 in prostate cancer progression, we examined KLK4 mRNA levels in several large clinical prostate cancer cohorts in publically available transcriptomic datasets." (PMID 33255452, 2020). "The serine protease kallikrein-related peptidase 4 (KLK4) has been reported to potentially play a role in the progression of prostate cancer and other cancer types." (PMID 33255452, 2020). "Recent reports have suggested the role of kallikrein-related peptidase 4 (KLK4) to be that of remodeling the tumor microenvironment in many cancers, including prostate cancer." (PMID 33255452, 2020). "In this study, we used in vivo models of prostate cancer and demonstrated that KLK4 can strongly inhibit the growth of primary prostate tumors as well as bone metastases." (PMID 33255452, 2020). "KLK4 expression has been revealed to be correlated to cellular progression of prostate cancer, and its elevation proposes KLK4 as a promising biomarker for the immune intervention." (PMID 31007611, 2019). "Activation of AR induces Klk4 transcription in prostate cancer cells, while activation of PR does so in breast cancer cells." (PMID 29249975, 2017). "The Kallikrein-related peptidase, KLK4, has been shown to be significantly overexpressed in prostate tumours in numerous studies and is suggested to be a potential biomarker for prostate cancer." (PMID 22970239, 2012). "Ectopic expression of KLK-4 in prostate cancer cells increased the proliferation rate and motility of cells, while overexpression of KLK-4 resulted in a decrease of E-cadherin expression and increase of vimentin expression signaling, a potential EMT event." (PMID 22641253, 2012). "Of note, KLK4 stimulates protease-activated receptors −1 and −2 which are also overexpressed in prostate cancer, resulting in cytoskeletal remodelling and increased cell migration and proliferation." (PMID 21556330, 2011). "Recently, we re-engineered the contact β-sheet of SFTI-1 to produce a selective inhibitor of kallikrein-related peptidase 4 (KLK4), a protease associated with prostate cancer progression." (PMID 21556330, 2011). "One KLK of interest, KLK4, is principally expressed in basal and secretory cells of the prostate gland and is commonly overexpressed in malignant prostate tumours." (PMID 21556330, 2011). "Three proteins were associated with risk of prostate cancer: GP2, TSPAN1, and FLT3LG [1.29 (1.21–1.36), 1.14 (1.09–1.18), and 0.87 (0.82–0.92)] and three were associated with endometrial cancer: CHRDL2, KLK4, and WFIKKN1 [1.42 (1.21–1.65), 1.41 (1.20–1.65), and 1.42 (1.20–1.68)]." (PMID 38750076, 2024). "Recently, we showed that at least five different KLK4 transcripts are expressed in prostate cancer tissues with the reference transcript encoding the classical KLK4 protease (pre-pro-KLK4) not being the predominantly expressed form of KLK4." (PMID 33255452, 2020). "Collectively, this clinical evidence correlates low KLK4 levels with prostate cancer progression." (PMID 33255452, 2020). "Kallikrein-related peptidase 4 (KLK4), a trypsin-like serine protease which is secreted by epithelial cells into their microenvironment, has been reported to have paradoxical effects in prostate cancer (PCa)." (PMID 33255452, 2020). "Notably, these studies have suggested a pro-tumorigenic role for KLK4, especially in prostate cancer." (PMID 33255452, 2020). "Herein, we employed an orthotopic inoculation xenograft model to mimic the growth of primary tumors, and an intracardiac injection to induce metastatic dissemination to determine the in vivo tumorigenic effects of KLK4 overexpressed in PC3 prostate cancer cells." (PMID 33255452, 2020). "For instance, miR-378, could bind to KLK4 and thus participate in the development of prostate cancer as reported by a previous study." (PMID 31007611, 2019).
prostate carcinoma (continued). "Moreover, CCND1 is known to further negatively regulate the AR function, not only by directly binding to AR to inhibit transactivation of AR, but also by attenuating AR-induced upregulation of Klk4 in prostate cancer." (PMID 29249975, 2017). "As more specific roles in prostate cancer development are elucidated for KLK-4, there is considerable promise that their ease of detection could effectively be utilized to diagnose and treat prostate cancer with a panel of other biomarkers." (PMID 22641253, 2012). "Although no SNPs in KLK4 have been reported by GWAS to be associated with prostate cancer at genome-wide significance levels to date, commonly used GWAS chips only capture 22% - 44% of validated genetic variation in the locus with r2≥0.80." (PMID 22970239, 2012). "In addition, KLK4 has been proposed to play a role in prostate cancer progression through its involvement in epithelial-mesenchymal transition, a more aggressive phenotype, and metastases to bone." (PMID 22970239, 2012). "KLK4 may also play a role in prostate cancer progression through its involvement in epithelial-mesenchymal transition, a more aggressive phenotype, and metastases to bone." (PMID 22970239, 2012). "KLK4 has gained support as a potential biomarker for several hormone-dependent cancers, and for prostate cancer specifically, in that numerous studies have found KLK4 to be significantly overexpressed in prostate carcinoma tissues compared to benign prostatic hyperplasia and normal tissues." (PMID 22970239, 2012). "For example, in prostate cancer cells, expression of KLK3 and KLK4 results in loss of E-cadherin and induction of expression of the mesenchymal marker vimentin, a hallmark of epithelial-to-mesenchymal transitions, which is a critical step for cancer metastasis." (PMID 21072173, 2010). "However, in breast cancer, KLK4 is elevated which is also true for ovarian and prostate cancer." (PMID 24294176, 2013). "Although both the short and long isoforms have been found to be overexpressed in prostate cancer cells, the “long” 254 aa KLK4 protein is better able to discriminate between tumour and normal cells and hence may be the more biologically relevant isoform in prostate cancer." (PMID 22970239, 2012). "Therefore, targeted inhibition of KLK4 may present an avenue to new treatments for advanced prostate cancer." (PMID 21556330, 2011). "An ultrasensitive impedimetric immunosensor was fabricated using a poly(glycidyl methacrylate) (PGMA) polymer-covered indium tin oxide (ITO) platform for the quantification of kallikrein 4 (KLK4), an important prostate cancer biomarker." (PMID 40656884, 2025). "In conclusion, KLK2, KLK3, KLK4, KLK5, KLK11, and possibly KLK15 are important for normal prostate physiology but become reprogrammed in prostate cancer to drive tumor progression." (PMID 41516101, 2025). "Expression analysis of KLK4, KLK4T2, and KLKP1 transcripts in prostate cancer cell lines showed high levels of KLKP1 transcripts in the nucleus and in unfractionated cell extract, whereas it was almost completely absent in the cytoplasmatic fraction." (PMID 34884832, 2021). "The kallikrein-related peptidase 4 (KLK4) gene is considered an oncogene and plays an important role in the formation of many tumors, such as gastric cancer and prostate cancer." (PMID 32758256, 2020). "Our results point to the fact that KLK1, KLK2, and KLK14 (only in recurrent prostate cancer tissues) are underexpressed in prostate cancer tissues, while KLK3, KLK4, KLK8, and KLK9 are overexpressed in both recurrent and non-recurrent tissues." (PMID 33150763, 2020). "In this study, KLK1, KLK4, KLK9, and KLK14 were strongly decreased in prostate cancer samples compared with controls." (PMID 33150763, 2020). "Other genes identified as highly enriched in prostate cancer were TGM4, KLK2 and KLK4, the latter kalekrein-related proteins belonging to the same family as PSA (KLK3)." (PMID 26237329, 2015).
prostate carcinoma (continued). "We and others identified several targets of miR-331-3p in prostate cancer cells, including ErbB-2, DOHH and KLK4." (PMID 24142150, 2014). "However, a recent study has shown that this cleaved peptide may be a useful target in prostate cancer immunotherapy, with the KLK4 signal peptide successfully inducing and expanding the cytotoxic T lymphocyte response more readily than PSA or Prostatic Acid Phosphotase (PAP)." (PMID 22970239, 2012). "The authors mention that this result is notable considering KLK4 and KLK2 collaborate to stimulate cellular proliferation in prostate cancer." (PMID 22970239, 2012). "Although no KLK4 SNPs were statistically significantly associated with prostate cancer risk after Bonferroni correction (P<9×10−4), 7 SNPs were associated at the Ptrend<0.05 significance level and the majority of these displayed a modest decrease in prostate cancer risk of around 20%." (PMID 22970239, 2012). "In light of the potential role played by KLK4 (having a sequence homology of 31.64% with thrombin) in prostate cancer via activating either PAR1 or PAR228, we sought to develop a strategy, alternative to generating a KLK4-specific enzyme inhibitor, to prevent KLK4-stimulated activation of PAR1." (PMID 34373558, 2021). "In conclusion, we propose that KLK1, KLK2, KLK3 KLK4, KLK8, KLK9, and KLK14, which are differentially expressed in prostate cancer, could be used as promising biomarkers of prostate cancer progression." (PMID 33150763, 2020). "Hence we sought to comprehensively investigate the role of KLK4 in prostate cancer risk and tumour aggressiveness by genotyping the majority of validated genetic variation (±10 kb) around the KLK4 locus in a large prostate cancer study group and male controls not screened for PSA levels." (PMID 22970239, 2012). "With the experimental models used herein, we cannot comment on the potential function of KLK4 during the first steps of metastasis such as migration from the primary tumor and invasion of blood vessels nor the influence of KLK4 on the androgen axis, or vice versa, in prostate cancer." (PMID 33255452, 2020). "In our study, KLK2, KLK3, and KLK4 were identified as gene signatures for prostate cancer; KLK3 is a prostate-specific antigen that is a gold-standard clinical biomarker widely employed in the diagnosis and monitoring of prostate cancer; KLK2 showed promise as prostate cancer biomarker, as well." (PMID 32850691, 2020). "Of note is the reported finding that the serine protease kallikrein 4 (KLK4), which promotes prostate cancer growth, activated both the AR and mTORC1 axis due to negative interplay of KLK4 with the transcription factor PLZF (promyelocytic leukemia zinc finger)." (PMID 27557496, 2016).
breast carcinoma (9 papers, 2008 to 2024). "Both KLK4 mRNA and protein levels have been reported to be a prognostic marker in various types of cancer: in prostate, oral and breast cancer, overexpression of KLK4 protein and mRNA was associated with an unfavorable prognosis." (PMID 30811511, 2019). "As for breast cancer, increased expression of mir-378 and of KLK-4 were independently and negatively correlated with prognosis in triple-negative breast cancer." (PMID 38338777, 2024). "In contrast, for breast cancer, at the mRNA level, eleven KLKs were found to be down regulated, while KLK4 and KLK15 mRNAs were overexpressed compared to normal breast tissue." (PMID 24294176, 2013). "PR induces Klk4 expression in breast cancer cells through direct binding to the Klk4 promoter." (PMID 29249975, 2017).
amelogenesis imperfecta (5 papers, 2009 to 2025). Amelogenesis imperfecta (AI) represents a group of developmental conditions affecting the structure and clinical appearance of the enamel of all or nearly all the teeth in a more or less equal manner, and which may be associated with morphologic or biochemical changes elsewhere in the body. "Mutations in the KLK4 gene were shown to be associated with the autosomal recessive form of amelogenesis imperfecta." (PMID 36422720, 2023). "Mutations in genes involved in enamel formation, such as enamelin (ENAM), amelogenin (AMELX), matrix metalloproteinase-20 (MMP-20) and kallikrein-related peptidase (KLK4), were associated with amelogenesis imperfecta." (PMID 28697775, 2017). "Mutations in the genes for amelogenin (AMELX), enamelin (ENAM), enamelysin (MMP20), and kallikrein 4 (KLK4) are known to cause defects in enamel that are collectively referred to as amelogenesis imperfectas." (PMID 19730686, 2009).
colon cancer (5 papers, 2016 to 2021). "Several members of kallikrein family are overexpressed in colon cancer patients, i.e., KLK4, KLK6, KLK7, KLK10, and KLK14." (PMID 34065672, 2021). "For instance, KLK4 dysregulation was detected in colon cancer and induced PAR1 signalling in caner." (PMID 30267012, 2018).
dental caries (5 papers, 2020 to 2026). The decay of a tooth, in which it becomes softened, discolored, and/or porous. "Dental caries in primary dentition was associated with SNPs in AMELX (rs17878486) and KLK4 (rs198968, rs2242670), and dental caries in permanent dentition with SNPs in AMELX (rs17878486) and KLK4 (rs2235091, rs2242670, rs2978642), (p ≤ 0.05)." (PMID 36422720, 2023). "In our study, 4 SNPs in KLK4 were analyzed, each of which was associated with the development of dental caries." (PMID 36422720, 2023). "The literature review also shows that AMELX and KLK4 variabilities have been associated with dental caries more often than variabilities in other genes." (PMID 36422720, 2023). "Based on this study, we found that although the SNPs in AMELX and KLK4 are localized in intronic regions and their functional significance has not yet been determined, they are associated with susceptibility to dental caries in children." (PMID 36422720, 2023). "In their study, SNP in KLK4 (rs2242670) was associated with dental caries in the permanent dentition; the AA genotype and combination of AA + AG genotypes were identified as risk factors." (PMID 36422720, 2023). "AMELX and KLK4 variants could be considered in the risk assessment of dental caries, especially in permanent dentition, in the European Caucasian population." (PMID 36422720, 2023). "Some KLK4 haplotypes were associated with dental caries in permanent dentition (p ≤ 0.05)." (PMID 36422720, 2023). "In conclusion, significant associations were found between the occurrence of dental caries, the SNP in AMELX (rs17878486), and some SNPs in KLK4 (rs198968, rs2235091, rs2242670, and rs2978642)." (PMID 36422720, 2023). "In this case–control study, 15 SNPs in ALOX15, AMBN, AMELX, KLK4, TFIP11, and TUFT1 genes were analyzed in 150 children with primary dentition and 611 children with permanent teeth with/without dental caries from the European Longitudinal Study of Pregnancy and Childhood (ELSPAC) cohort." (PMID 36422720, 2023).
prostate tumors (5 papers, 2012 to 2025). "Only one KLK4 SNP, rs198968, was associated with prostate tumour aggressiveness (Gleason score <7 vs. ≥7: OR 0.76 (95% CI 0.60–0.95, Ptrend = 0.016)." (PMID 22970239, 2012). "Association of KLK4 SNPs and prostate tumour aggressiveness." (PMID 22970239, 2012). "Of these epithelial cell clusters, two subclusters of LE cells (LE KLK3+ and LE KLK4+) were representative of prostate tumors." (PMID 40723207, 2025). "These discrepancies between studies investigating the function of KLK4 in prostate tumors can be attributed likely to the diverse methodologies employed." (PMID 33255452, 2020). "Of note, KLK4 is known to be expressed as a variety of isoforms, with the full length protein (254 amino acids long) showing the potential to be a better biomarker of prostate tumour cells than the commonly expressed shorter isoform (205 amino acids)." (PMID 22970239, 2012). "There are several studies reporting that the expression of KLK4 is higher in prostate tumors compared to normal, nonmalignant prostate tissue." (PMID 34884832, 2021).
oral squamous cell carcinoma (4 papers, 2021 to 2022). "Downregulation of KLK4 results in decreased migration and invasion in oral squamous cell carcinoma cells." (PMID 34561425, 2021). "miR-378a-5p suppresses angiogenesis in oral squamous cell carcinoma by regulating of Kallikrein-related peptidase 4 (KLK4)." (PMID 34749775, 2021). "Inhibition of KLK4 suppresses the growth of oral squamous cell carcinoma cells through the Wnt/β-catenin pathway." (PMID 34561425, 2021). "Besides, miR-378a-5p also inhibits angiogenesis through targeting Kallikrein-related peptidase 4 (KLK4) in oral squamous cell carcinoma cells." (PMID 34587874, 2021).
prostate adenocarcinoma (3 papers, 2018 to 2025). "Prostate adenocarcinoma and urothelial bladder carcinoma exhibited significant up-regulation of KLK2 and KLK4 gene expressions (KLK2: 3-fold and 2-fold, KLK4: 3-fold and 2-fold)." (PMID 29707153, 2018). "In prostate adenocarcinoma (PRAD), the family of KLK genes KLK2, KLK3, and KLK4 are enriched in both the prostate and prostate cancer." (PMID 40453216, 2025).
colorectal adenocarcinoma (2 papers, 2021 to 2025). The most common type of colorectal carcinoma. "The top hit between AD and HC groups, KLK4, kallikrein‐related peptidase 4, has been implicated in many types of cancer and has potential as a tumor biomarker which also predicts short‐term relapse in colorectal adenocarcinoma patients." (PMID 33107199, 2021). "The independent prediction of short-term relapse but not of disease-related death has also been shown for other candidate biomarkers in colorectal adenocarcinoma, including kallikrein-related peptidase 4 (KLK4) mRNA and miR-24-3p expression." (PMID 41153715, 2025).
esophageal cancer (2 papers, 2018 to 2021). A primary or metastatic malignant neoplasm involving the esophagus. "In each of the following cancers, only one KLK was significantly upregulated: hepatocellular carcinoma (KLK4: 2-fold), stomach adenocarcinoma (KLK6: 11-fold) and esophageal carcinoma (KLK4: 3-fold)." (PMID 29707153, 2018). "In our analysis KLK4 expression was increased 3-fold in esophageal carcinoma." (PMID 29707153, 2018).
serous ovarian cancer (2 papers, 2013 to 2019). "Association between KLK4 mRNA expression levels and clinical characteristics in patients with advanced high-grade serous ovarian cancer (FIGO stage III/IV)." (PMID 30811511, 2019). "In the present study, we found a significant association of elevated KLK4 mRNA expression levels with shortened OS analyzing a homogenous cohort of advanced high-grade serous ovarian cancer patients (FIGO stage III/IV)." (PMID 30811511, 2019). "Our analyses of the correlations of KLK4 mRNA expression with clinical parameters demonstrated that KLK4 mRNA levels are significantly associated with the amount of pre-operative ascites fluid volume in advanced high-grade serous ovarian cancer." (PMID 30811511, 2019). "In the present retrospective study, we analyzed the mRNA expression levels of KLK4 in a homogenous cohort of 138 patients suffering from advanced high-grade serous ovarian cancer (FIGO stage III/IV) by qPCR." (PMID 30811511, 2019). "In the present study, we quantitatively analyzed KLK4 tumor tissue mRNA expression levels in a homogeneous cohort including 138 patients of advanced high-grade serous ovarian cancer (FIGO stage III/IV)." (PMID 30811511, 2019). "KLK4 mRNA expression levels were assessed in 138 tumor tissues of patients with advanced high-grade serous ovarian cancer (FIGO stage III/IV)." (PMID 30811511, 2019). "In previous studies, KLK4 protein was demonstrated to be upregulated in serous ovarian cancer, as compared with the expression in normal ovary tissues." (PMID 30811511, 2019). "In multivariable analysis, our data showed that apart from residual tumor mass, KLK4 mRNA was an independent prognostic indicator for poor OS (p = 0.006) in advanced high-grade serous ovarian cancer." (PMID 30811511, 2019). "In accordance with these data, in the current study KLK4 mRNA was detectable at low levels in most of the advanced high-grade serous ovarian cancer samples as well." (PMID 30811511, 2019).